TOP2A (DNA topoisomerase II alpha)
Diseases named in the same sentence as TOP2A in open-access papers (continued):
Sharing a sentence is not in itself a finding about the gene and the disease.
tumor (continued). "We further investigated TOP2A genetic alteration information through the online database cBioPortal in various tumor tissues dominated from TCGA datasets." (PMID 35778520, 2022). "Consistently, we noted a correlation between TOP2A, a vital tumour biomarker, and the FOXO signalling pathway." (PMID 36585615, 2022). "It has been shown that inhibition of TOP2A expression inhibits the proliferation of tumor cells in cellular experiments." (PMID 35774141, 2022). "Meanwhile, CAFs’ infiltration presented a statistically positive relationship with TOP2A expression in several tumor types, and this result manifested a potential role of CAFs in the tumor occurrence and promotion." (PMID 35778520, 2022). "Knockdown of TOP2A obviously inhibited MB cell proliferation, migration and invasion, and sensitised tumor cells to radiotherapy." (PMID 35912241, 2022). "Consistent with findings of previous studies in tumours, in the present study, we observed that TOP2A knockdown negatively effects trophoblast functions including proliferation, apoptosis, migration, and invasion." (PMID 36585615, 2022). "The ceRNA network targeting TOP2A has significant effects on tumor occurrence and development in several tumor types." (PMID 35778520, 2022). "By analyzing the effect of the expression level of TOP2A protein on the proliferation and invasion of tumor cells, the researchers found that the expression of TOP2A protein was closely related to the proliferation and invasion of LC cells." (PMID 35928585, 2022). "Out of all the candidates, KLC1 and TOP2A showed high levels of expression in every tumor type examined." (PMID 36010968, 2022). "Tumour cells with high TOP2A expression were highly sensitive to pirarubicin, and TOP2A+ HER2- cells were more sensitive to pirarubicin than TOP2A+ HER2+ cells." (PMID 35711974, 2022). "In recent years, a growing number of studies have shown that TOP2A is significantly higher in tumor tissue (P < 0.001) and significantly negatively correlated with prognosis in tumor patients (P = 0.002)." (PMID 35033076, 2022). "Consistent with mRNA expression profile, TOP2A protein expression determined by immunohistochemistry assay was also significantly up-regulated in 12 available tumor tissues." (PMID 35873470, 2022). "The expression profiles of genes in the first cluster across all tumours (TOP2A, CDK1, BIRC5, GPC3, IGF2 and AFP) were strongly correlated." (PMID 36345011, 2022). "The co-amplification of ERBB2 and TOP2A was assessed by shallow whole genome sequencing on tumor tissue whenever available." (PMID 35565244, 2022). "The results showed that the expression of TOP2A in tumor tissues was significantly higher than that in adjacent normal tissues, which was consistent with the results of the four GEO datasets." (PMID 35912241, 2022). "DNA double-strand breaks are the most lethal form of damage to tumor cells after radiotherapy, and several studies have shown that TOP2A is closely related to the therapeutic effects of radiation." (PMID 35912241, 2022). "In patients with medulloblastoma and breast cancer, tumours with high TOP2A expression levels are sensitive to anthracyclines and these drugs show good therapeutic effects." (PMID 35711974, 2022). "TOP2A is an isoform of the Topoisomerase II (TOP2), typically expressing at high levels in rapidly proliferating and growing cells, especially tumor cells, in which overexpression of TOP2A is associated with poor clinical outcomes." (PMID 36589233, 2022). "In tumours with high TOP2A expression, those with concurrent HER2 overexpression showed a higher recurrence rate, and the IC50 in the TOP2A+ HER2+ cells was higher than that in the TOP2A+ HER2- cells." (PMID 35711974, 2022). "Meanwhile, more ceRNA regulatory networks need to be explored for in-depth understanding of TOP2A’s molecular mechanism in multiple tumor types." (PMID 35778520, 2022).
tumor (continued). "The results revealed a higher S1106 phosphorylation level of TOP2A in all primary tumor tissues than in the normal tissues." (PMID 35873470, 2022). "In terms of gastric cancer, FAM230B has been confirmed to increase TOP2A expression via miR-27a-5p in tumor development and metastasis." (PMID 35778520, 2022). "In recent years, more and more research has shown that TOP2A significantly had expressed in tumor tissues (P < 0.001), and negatively correlated with the prognosis of patients with tumor (P = 0.002)." (PMID 35033076, 2022). "Meta-program A was characterized by markers of the cell cycle, such as Top2a and Mki67, indicating the presence of proliferating subpopulations of tumor cells in all tumors." (PMID 34210306, 2021). "As expected, loss of RHPN1-AS1 resulted in an increase in the expression of miR-485-5p and a decrease in the expression of TOP2A in tumor tissues from nude mice." (PMID 34787052, 2021). "Overexpression of TOP2A is correlated with a more aggressive tumor phenotype, microvascular invasion, and early age onset of HCC." (PMID 33868991, 2021). "The most consistently upregulated genes across multiple tumor types were TOP2A (FC = 7.8), SPP1 (FC = 7.0) and CENPA (FC = 6.03), and the most consistently downregulated gene was ADH1B (FC = 0.15)." (PMID 33807717, 2021). "TOP2A was upregulated in tumor tissues 31, correlated with the poor survival of PC patients, and induced PC cell progression." (PMID 34326696, 2021). "We have discovered four genes of prognostic value (CENPF, FOXM1, MCM4, and TOP2A), and further prioritized MCM4 as a key biomarker of LPS associated with tumor invasiveness (tumor stage, grade, and Ki67 labeling index) and prognostication." (PMID 34178990, 2021). "As part of this study, they also developed an “A-score” comprised of a TOP2A gene signature and two signatures related to tumor invasion and immune response." (PMID 34625570, 2021). "The significance of TOP2A in tumor aggressiveness and chemoresistance indicate that the mechanisms through which it functions require further exploration." (PMID 32685486, 2020). "High expression of DNA topoisomerase II alpha (TOP2A) was detected in 72.5% of HCC tumor tissues and an increase in TOP2A expression is correlated with shorter survival of patients and chemoresistance." (PMID 32046048, 2020). "A study on adrenocortical carcinoma (ACC) manifested that aclarubicin was the best agent of 14 TOP2A inhibitors that can decrease proliferation and tumor spheroid size in locally advanced and metastatic ACC." (PMID 33376723, 2020). "TOP2α is abundantly expressed in the tumor tissues; therefore, a combination of DOX and TOP2α is the molecular basis for eliminating tumor cells." (PMID 33132907, 2020). "In each case, 2 patients (4.8%) harbored CNV in all 3 exons of EGFR and FGFR1, and only one patient (2.4%) had CNV in both exons of TOP2A, suggesting that the whole genes were possibly amplified in the primary tumor." (PMID 33298978, 2020). "Consistent with the expression results analyzed by ONCOMINE, the expression levels of CDK1, CCNB1, CCNB2, MAD2L1, and TOP2A assessed by TCGA data were all upregulated in tumor tissues compared with the normal controls (all P < 0.05)." (PMID 31886163, 2019). "This table included the diameter and volume of the tumor sizes in control group and TOP2A knockdown group, which were measured as indicated in the methods section." (PMID 31216997, 2019). "There was a clear trend of increasing gene expression levels of MET, MELK, SDC1 and TOP2A in primary tumor compared to normal samples." (PMID 31412643, 2019). "Increased TOP2A expression, observed in ~35% of samples, correlates with increasing tumor grade, and is predictive of anthracycline responsiveness." (PMID 31970090, 2019). "TOP2A signal localized mainly in the nucleus and to a lesser extent in the cytoplasm of tumor cells." (PMID 31816603, 2019).
tumor (continued). "It is expected that the expression of wild type Top2α and Top2β decreases in chemotherapeutic resistant tumor cells." (PMID 31791417, 2019). "Compared with normal tissues, the tumor samples appeared to have higher levels in the expression profiling of TOP2α." (PMID 31662984, 2019). "In the present study, our RNA-Seq data of ten pairs of BLCA samples identified TOP2A gene were significantly upregulated in the tumor samples compared with the matched normal epithelial tissue." (PMID 31216997, 2019). "Several studies indicate that altered expression of TOP2A in tumor tissue was a prognostic biomarker for multiple cancers." (PMID 31737106, 2019). "Of the 209 tumor samples, high (staining score, 2.23 ± 0.42) and low (staining score, 0.95 ± 0.22) TOP2A expression was found in 99 and 110 patients, respectively." (PMID 31216997, 2019). "Whereas, the expression of PRC1 and TOP2A in HBV-related HCC tumor tissue was markedly upregulated in the GSE14520 cohort, and also up-regulation in advance tumor stage samples." (PMID 31737106, 2019). "We found that TOP2A was significantly up-regulated in tumor samples, especially higher for MIBC and high-grade tumors." (PMID 31216997, 2019). "TOP2A is highly expressed in dividing cells, and is considered as a proliferation marker in both normal and tumor cells." (PMID 31816603, 2019). "We identified TOP2A was up-regulated in nine out of ten tumor samples with a log2-fold change of 3.02 and probability of 0.86." (PMID 31216997, 2019). "The difference of tumor volume between TOP2A knockdown group and control group was statistically significant 6 weeks after tumor cells implantation." (PMID 31216997, 2019). "In terms of diagnosis, previous studies also reveal that TOP2A has notably increased expression in HCC tumor tissues 65, 66 compared to the adjacent normal liver tissues." (PMID 31737106, 2019). "Results showed that ERBB2 and TOP2α gene status are highly correlated (r=0.87, p<0.0001, n=25), with few tumor samples presenting amplification." (PMID 31301170, 2019). "TOP2A levels were 753 amol/μg (IQR 492-936) in RAS wild-type and 441 amol/μg (IQT 354-587) in mutated tumours." (PMID 31537838, 2019). "The tissue type and the tumor microenvironment have different effects on the process of carcinogenesis due to the different roles of TOP2A." (PMID 30544723, 2018). "The tumor suppressor BRCA1 was shown to reduce Top2α activity through its E3 ubiquitin ligase activity." (PMID 29915179, 2018). "In our study, there was a majority of HCMV-positive tumor tissues expressing high levels of TOP2A mRNA compared to HCMV-negative control tissues." (PMID 30544723, 2018). "There are a few reports directly linking TOP2A gene expression level and tumor hematogenous recurrence." (PMID 28915696, 2017). "TOP2A was discovered to be the target of many anti-tumor drugs which had already been widely used in clinic." (PMID 28106765, 2017). "This suggestion came from the finding that higher expression of TOP2A correlated with poor tumor grade and high recurrence score based on the Oncotype Dx signature." (PMID 28832682, 2017). "Based on these results, the expression of TOP2A was significantly greater in CR than CN tumor cells (approx 1.5 fold)." (PMID 27470985, 2016). "We quantitatively detected the anticancer effect of DDP/VP-16, mRNA and protein expression of ERCC1/TOP2A in C57BL/6 mice with tumor and in human NSCLC A549 cells, as well as in RNAi A549 cells." (PMID 27895586, 2016). "Excessive HSA significantly up-regulated the protein expression of ERCC1 and TOP2A respectively in mice with tumor." (PMID 27895586, 2016). "TOP2A knockdown reversed both the anti-tumor effect and significantly reduced DNA damage induced by selinexor/doxorubicin treatment." (PMID 27557643, 2016). "From the Oncomine database, we also found widespread upregulation in the expression of TOP1 and TOP2A genes in primary tumor tissues." (PMID 27315793, 2016).
tumor (continued). "This elevated expression was consistent with the proteomic profiling analysis, in which the Rsc (CR/CN) value of TOP2A was 3.7 fold higher in CR compared to CN tumor cells." (PMID 27470985, 2016). "TOP2A poisons killed tumor cells more efficiently early in the progression course, while at later stages they provided greater benefit when combined with anti-androgen therapy." (PMID 26560244, 2015). "We show that TOP2A promotes tumor aggressiveness by inducing chromosomal rearrangements of genes that contribute to a more invasive phenotype." (PMID 26560244, 2015). "Mechanistically, we find that TOP2A enhances androgen signaling by facilitating transcription of androgen responsive genes, thereby promoting tumor cell growth." (PMID 26560244, 2015). "In the TN group, 75 % of the tumor samples (12/16) showed results indicative of allelic instability of the HER2/TOP2A locus." (PMID 26022247, 2015). "One of the tumor tissues with TOP2A gene deletion showed TOP2A overexpression (Case 32), whereas the other tumor tissue showed no expression of TOP2A (Case 34)." (PMID 25695068, 2015). "In this study, we developed a cell model to examine role of TOP2A in tumor progression and assess its contribution to cell sensitivity to hormonal and chemotherapy." (PMID 26560244, 2015). "This significant increase of Top2a expression was validated by qRT-PCR from RNA samples used for RNA-seq, as well as additional independent tumor samples (p=0.04)." (PMID 25605014, 2015). "We endeavor to develop a simple and facile screening based on the measurement of fluorescence anisotropy to discover effective anti-tumor drugs targeting Top2α." (PMID 24809695, 2014). "Consistently, the present study showed that knocking down expression of TOP2A markedly suppresses cell proliferation in vitro and tumor growth in vivo." (PMID 25237769, 2014). "TOP2A protein expression was detected in 36.4% (28/77) of tumor tissues, which was significantly higher as compared with that observed in normal tissues." (PMID 25202398, 2014). "To gain further insight into the function of TOP2A in tumor cells, we knocked down TOP2A in DU145 cells." (PMID 25237769, 2014). "The sensitivity or resistance of a malignant cell to these anti tumor drugs, also called topo II poisons, is proportional to the level of TOP2A expression." (PMID 23398928, 2013). "In a multivariate model (AUC: 0.78), the TOP2A/β-tubulin combination index score remained statistically significantly related to tumor response (p < 0.001) as well as estrogen receptor status ( p = 0.014) and grade ( p = 0.016)." (PMID 22578285, 2012). "Discordances between HR expression, HER2 and TOP2A status in CTCs and their primary tumor were found in the sequential blood samples." (PMID 22554015, 2012). "Based on our multivariate analysis, our data suggests the TOP2A and β-tubulin indices remain predictive even after adjusting for clinical parameters such as tumor grade and estrogen receptor status, indicating that these indices likely have clinical value." (PMID 22578285, 2012). "All these drugs have been shown to sensitize other tumor entities to antitumoral effects of TOP2A inhibitors, purportedly by increasing TOP2A expression levels." (PMID 23300809, 2012). "Expression of TOP2A was nuclear both in the tumor cells and in the acinar and ductal epithelial cells present in the histologically normal breast tissues with high-grade and low-grade molecular abnormality." (PMID 21785684, 2011). "Previous publications show that Top2α level is reduced at physiological conditions such as glucose deprivation and hypoxia that are common in the tumor environment, and that this leads to decreased efficacy of the Top2-directed drugs." (PMID 19956605, 2009).
tumor (continued). "The Kaplan-Meier estimates of time to tumor recurrence for patients with TOP2A deletion versus others are shown." (PMID 18702822, 2008). "The TOP2A gene, which is located near HER2 on chromosome 17, is the target of many chemotherapeutic agents, and co-amplification of HER2 and TOP2A has been described in several tumor types." (PMID 19061514, 2008). "This notion has been strengthened by a subgroup analysis of the BCIRG-006 study, suggesting that the combination of trastuzumab/doxorubicin is only superior to trastuzumab/docetaxel in tumours harbouring an amplification of TOP2A." (PMID 17088909, 2006). "A total of 194 patients, from whom information on TOP2A gene amplification, chemotherapy treatment and clinical follow-up were available, had tumours with HER2 gene amplification." (PMID 17088909, 2006). "In the study presented here, we determined the amplification status of TOP2A in all HER2-positive tumours of the patient cohort of the Dutch National trial of high-dose chemotherapy." (PMID 17088909, 2006). "The TOP2A amplification status was assessed by CISH or FISH in the subgroup of HER2-positive tumours (n=194)." (PMID 17088909, 2006). "We subsequently determined the survival-rates for the HER2-positive tumours of this patient cohort after conventional-dose and high-dose chemotherapy dependent on the TOP2A gene amplification status of the tumours." (PMID 17088909, 2006). "We therefore examined the presence of a (recurrence-free) survival advantage for patients with TOP2A-amplified tumours in the conventional-dose arm over those in the high-dose arm that contained a 20% lower cumulative dose of anthracyclines." (PMID 17088909, 2006). "Concurrently, tumor tissue and primary cultures displayed low transcript levels of proliferation-related genes, such as, TOP2A, ANKT, RAD51, UBE2C, CENPA, RRM2, and PLK." (PMID 15260889, 2004). "Moreover, elevated TOP2A levels were linked to a higher TNM stage and deeper tumor invasion, suggesting a potential role in tumor aggressiveness." (PMID 40765849, 2025). "Given the strong associations between TOP2A expression and both TNM stage and tumor invasion depth, future studies could explore whether combining TOP2A with TNM staging may offer comparable or even superior prognostic value." (PMID 40765849, 2025). "Specifically, the average tumor size was 3,256.5 mm3 in the CpG group, while it was reduced to 1,649.7 mm3 in the TOP2A group (p<0.01), 2,242.5 mm3 in the IGF-1R group, 1,703.2 mm3 in the HIF-1α group (p < 0.05), and down to 361.7 mm3 in the TNBCvax group (p<0.0001)." (PMID 40969744, 2025). "Moreover, TCGA-STAD data indicated that both MYC and TOP2A were markedly upregulated in tumor tissues compared to adjacent normal tissues." (PMID 40290723, 2025). "Since we found that knockdown of UBE2C reduced the expression of TOP2A, we speculated that inhibiting UBE2C might have a synergistic effect with doxorubicin, enhancing its ability to inhibit TOP2A expression and reach a better anti‐tumor effect." (PMID 40729680, 2025). "Therefore, TOP2A is involved in tumor progression as an oncogene, and NCTD likely target TOP2A to inhibit its expression, thereby inhibiting tumor progression." (PMID 40271060, 2025). "TOP2A plays a carcinogenic role in a variety of tumor types." (PMID 41284119, 2025). "The use of a TOP2A-specific poison or anthracycline derivative could restrict cytotoxicity to tumour cells that express high levels of TOP2A and would be highly desirable." (PMID 40425539, 2025). "Additionally, we observed that the cell proliferation markers MKI67 and TOP2A were highly expressed in spatial cluster C5, which was exclusively located in the tumor region." (PMID 39950944, 2025). "It was reported that once the TOP2A expression level decreased, the β-catenin level was also downregulated, indicating that the Wnt/β-catenin signaling pathway was inhibited, suggesting that the reduction of TOP2A level is beneficial to improve the prognosis of tumor patients." (PMID 41284119, 2025).